APP (amyloid beta precursor protein)
Diseases named in the same sentence as APP in open-access papers (continued):
Sharing a sentence is not in itself a finding about the gene and the disease.
Alzheimer disease (continued). "Stage of clinical development of anti-APP drugs to treat Alzheimer’s disease." (PMID 37307834, 2024). "According to the mitochondrial cascade hypothesis, age-related loss of mitochondrial function affects the expression and processing of APP, producing amyloid beta oligomers that accumulate in atherosclerotic plaques in Alzheimer’s disease." (PMID 38457008, 2024). "Likewise, Cxcr3 signaling in an APP/Ps1 mouse model of Alzheimer’s disease has been shown to increase plaque formation and reduce microglial phagocytosis of plaques." (PMID 39091874, 2024). "In APP/PS1 Alzheimer's disease model mouse neurons, FLIM revealed strikingly different AMPAR trafficking properties for GluA1- and GluA3-containing receptors, suggesting that chronic Aβ exposure triggered the loss of both surface and intracellular GluA3-containing receptors." (PMID 38915938, 2024). "It illustrates how APP is cleaved by β- and γ-secretases to release Aβ peptides, which, subsequently, aggregate in the extracellular space, forming the amyloid plaques that are characteristic of Alzheimer’s disease pathology." (PMID 39684324, 2024). "Pathway insights into the distinct cerebral responses were gained through a systematic quantitative analysis of the expression of 90 genes related to canonical Alzheimer’s disease, neurometabolic, and neuroinflammatory pathways in the brains of WT and APP/PS1 mice." (PMID 39519239, 2024). "The subtype A1 has been shown to be related to Alzheimer’s disease, as it may contribute to generating soluble APP, which mediates tau phosphorylation and has been found in dystrophic neurites and degenerating neurons near tau tangles." (PMID 38276010, 2024). "The APP/PS1 double-transgenic mouse model is a well-established model for Alzheimer’s disease." (PMID 38440398, 2024). "This interaction implies that these polyphenols may regulate the activity of APP and the generation of amyloid-beta, thereby decreasing symptoms resembling Alzheimer’s disease in individuals with Down Syndrome." (PMID 39204195, 2024). "Notably, γ-secretase plays a critical role in the pathogenesis of Alzheimer’s disease through its implication in the processing of the β-amyloid precursor protein (APP)." (PMID 38089466, 2024). "Our results demonstrated that the attenuation of experimental Alzheimer's disease following CR treatment in APP/PS1 mice may result from alterations in the gut microbiome." (PMID 38992870, 2024). "The treatment of Alzheimer's disease transgenic mice expressing mutant human amyloid precursor protein (APP) and presenilin-1 (PS1) with the DQ detoxification cocktail selectively eliminated senescent cells and reduced neuroinflammation while improving cognitive deficits." (PMID 37450933, 2024). "This dysfunction may underlie the neurological and cognitive impairment in DS, contributing to decreased neurogenesis and altered processing of APP, leading to deposition of Aβ amyloid and early-onset Alzheimer's disease." (PMID 38266108, 2024). "APP (amyloid precursor protein) is cleaved on an amyloidogenic pathway by β-secretases and γ-secretases to produce insoluble Aβ fibrils that aggregate into plaques that are one of the pathomechanisms of Alzheimer’s disease." (PMID 38792524, 2024). "APP/PS1 transgenic mouse model harbors familial mutations in both the APP (695swe) and PS1 (dE9) genes, exhibiting overproduction of amyloid-beta (Aβ), formation of plaque deposits and other pathological features characteristic of Alzheimer's disease." (PMID 39656489, 2024). "We set out to test whether dox treatment used to control transgene expression in our APP/TTA model of Alzheimer’s disease might affect brain phenotypes by altering the gut microbiome." (PMID 38178148, 2024).
Alzheimer disease (continued). "3xTg: One of the most used AD models is the triple transgenic (3xTg) mouse, which replicates both the tau and Aβ pathologies; Tg-ArcSwe: transgenic mice with the Arctic and Swedish Alzheimer mutations; R1.40, APP/PS1, P301S: these are commonly used mouse models in Alzheimer's Disease." (PMID 39286668, 2024). "In the brains of Alzheimer’s disease (AD) patients, amyloid-beta (Aβ) peptides are produced by sequential proteolytic cleavages of a membrane-bound protein called amyloid-beta precursor protein (APP) by proteases known as β-secretase and γ-secretase." (PMID 39861653, 2024). "Notably, all successful mouse models of Alzheimer’s disease express either mutant human Aβ or a humanized version of the APP gene." (PMID 39595581, 2024). "Additionally, an in vivo study reported the use of a linear polyethyleneimine (LPEI)-g-polyethylene glycol (PEG) copolymer-based micellar nanoparticle system to deliver siRNA targeting BACE1 and APP, two key therapeutic targets in Alzheimer’s disease." (PMID 39204177, 2024). "Additionally, LA has been found to improve memory deficits and cognitive decline in APP/PS1 transgenic mice with Alzheimer’s disease by inhibiting the production of inflammatory factors and reducing the deposition of beta-amyloid protein." (PMID 38398662, 2024). "Recently, we observed the ability of TSA, to reverse the hypoacetylation of histone H4 (H4K12) in the hippocampus and increase albumin expression and Aβ clearance, as well as ameliorate Alzheimer’s disease-related pathology and cognitive deficits in APP/PS1 mice." (PMID 38572429, 2024). "APP’s processing and the subsequent accumulation of Aβ could therefore be a shared pathological feature in PD and Alzheimer’s disease." (PMID 39264583, 2024). "Importantly, many further studies have demonstrated that disruption of APP transport is an early feature in Alzheimer’s disease and it promotes amyloidogenic processing of APP, moreover, altered processing of APP itself disrupts axonal transport." (PMID 39520508, 2024). "5XFAD mice, 3xTg mice, and APP/PS1 mice are widely used as Alzheimer’s disease model mice." (PMID 38548872, 2024). "Moreover, PARP16, function as a RNA binding protein, modulates the mRNA stability of amyloid precursor protein (APP), the precursor of beta-amyloid (Aβ) and prevents modified APP from degradation in Alzheimer’s disease (AD) mice." (PMID 38734665, 2024). "Alzheimer’s disease (AD) is characterized by the aggregation of amyloid β (Aβ) peptides and the formation of plaques in the brain, primarily derived from the proteolytic degradation of amyloid precursor protein (APP)." (PMID 39700174, 2024). "The 5xFAD mouse model of AD overexpresses mutant human amyloid precursor protein (APP) containing the Swedish (K670N, M67IL), Florida (I716V), and London (V717I) Familial Alzheimer’s Disease (FAD) mutations, as well as the human presenilin 1 (PS1) gene with two FAD mutations, M146L and L286V." (PMID 39456417, 2024). "Here, we used the ML-based variational animal motion embedding (VAME) segmentation platform to assess spontaneous behavior in humanized App knockin and transgenic APP models of Alzheimer’s disease (AD) and to test the role of AD-related neuroinflammation in these behavioral manifestations." (PMID 39427315, 2024). "Amyloid plaques, a major pathological hallmark of Alzheimer's disease (AD), are caused by an imbalance between the amyloidogenic and non-amyloidogenic pathways of amyloid precursor protein (APP)." (PMID 38994634, 2024). "In various mouse models, including amyloid protein precursor (APP) transgenic mice (6 J/cm2), Aβ-induced Alzheimer’s disease (AD) mice (3 J/cm2), and a major depression (41 J/cm2) mouse model, cerebral ATP levels were augmented utilizing transcranial PBM therapy with an 808 nm laser." (PMID 38891098, 2024). "We tested 7 months KD vs. control diet (CD) in the mouse Alzheimer’s Disease (AD) model APP/PS1." (PMID 38366025, 2024).
Alzheimer disease (continued). "In our study, markers of ER stress were upregulated in the cortex and hippocampus of APP/PS1 mice, in line with the observations that ER stress is associated Alzheimer’s disease pathology and may potentiate cell loss in the disease." (PMID 37163422, 2023). "Moreover, within a single substrate, APP, and with one enzyme, presenilin-1, multiple cut sites are thought to affect downstream Alzheimer's disease progression." (PMID 38270390, 2023). "Alzheimer’s disease (AD) is characterized by the presence of tau protein inclusions and amyloid beta (Aβ) plaques in the brain, with Aβ peptides generated by cleavage of the amyloid precursor protein (APP) by BACE1 and γ-secretase." (PMID 37269953, 2023). "Phosphorylated-tau and APP are involved in Alzheimer’s disease (AD) pathogenesis." (PMID 38036591, 2023). "Interestingly, recent research on the APP/PS1 mice with Alzheimer’s disease (AD) have demonstrated that CHZ daily administration during 23 days significantly improved the MWM performance of AD mice." (PMID 37537226, 2023). "The major hypothesis implicates the defective cleavage of amyloid precursor protein (APP) and the consequent amyloid beta plaque formation as a predominant basis for Alzheimer’s disease, giving rise to a downstream cascade that leads to tau-pathology." (PMID 37834241, 2023). "Furthermore, a specific mechanism involving TRPA1 and Alzheimer’s disease (AD) was demonstrated using APP/PS1 Tg/TRPA1 KO mice." (PMID 37296632, 2023). "Methylation of APP can effectively reverse the symptoms of Alzheimer's disease." (PMID 37356052, 2023). "APP has been extensively studied for its role as the precursor of Aβ in Alzheimer’s disease." (PMID 37836528, 2023). "Additionally, genetic factors, such as mutations in genes like amyloid precursor protein (APP) and presenilin 1 and 2 (PSEN1 and PSEN2), can further increase the risk of developing Alzheimer’s disease." (PMID 37688657, 2023). "Experiments on transgenic mice with an Alzheimer’s disease model (APP/PS1) demonstrated that the intranasal administration of liposomes within 21 days resulted in enhanced learning abilities and a reduction in the formation rate of Aβ plaques in the entorhinal cortex and hippocampus of the brain." (PMID 37445673, 2023). "Meanwhile, the miR-20a family may promote the development of Alzheimer’s disease by targeting the Amyloid Precursor Protein (APP)." (PMID 38139051, 2023). "Significant evidence implicates APP cleavage in Alzheimer’s disease pathogenesis." (PMID 37923712, 2023). "We found VUS in the ABCA1, APP and GC genes, the three reported as altered in Alzheimer’s disease." (PMID 37784196, 2023). "In the APP/PS1 mouse model of Alzheimer’s disease, the number of CR4 transcripts and CR4-positive microglia increased sharply and in parallel to the increasing Aβ plaque load with age, and their transcriptional profile showed an increase in immunosuppressive markers." (PMID 37308987, 2023). "In summary, APP gencDNA transcripts, including L-APP in plasma, may serve as blood biomarkers for Alzheimer's disease and detect the early clinical or pre-clinical stages of Alzheimer's disease." (PMID 38066066, 2023). "Due to mutations in APP and genetic risk genes, such as PSEN1 and PSEN2 which alter amyloid concentrations, patients with DS are more prone to develop Alzheimer’s disease at an earlier age (30–60 years) than those with late-onset Alzheimer’s disease (≥65 years)." (PMID 37238612, 2023). "We used the adenovirus containing thyrotropin receptor (TSHR) amino acid residues 1-289 (Ad-TSHR289)-induced Graves’ disease (GD) phenotype in Alzheimer’s disease (AD) model mice (APP/PS1 mice) to evaluate the effect of hyperthyroidism on the cognitive function and β-amyloid (Aβ) accumulation." (PMID 37740205, 2023). "Indeed, in the APP[V717I] Alzheimer’s disease mouse model, NtB PACAP administration improves cognitive performances and increases the processing of APP through the non-amyloidogenic pathway." (PMID 37631246, 2023).
Alzheimer disease (continued). "Another study reported nine somatic mutations in the amyloid beta precursor protein (APP), sortilin-related receptor 1 (SORL1), nicastrin (NCSTN) and microtubule affinity-regulating kinase 4 (MARK4) genes in patients with Alzheimer’s disease by next-generation sequencing (NGS)." (PMID 37834279, 2023). "The impact of discovering mutations of APP, PS1, and PS2 genes was profound, but the relevance of data from the observational and therapeutic studies with autosomal dominant mutation carriers to sporadic Alzheimer’s disease has gradually become less tenable." (PMID 37693644, 2023). "The increased APP expression associated with SGLT2 mutations may provide a good model with which to investigate the relationship between glucose metabolism and Alzheimer’s disease." (PMID 37047250, 2023). "In an amyloid precursor protein/presenilin-1 (APP/PS1) mouse model of Alzheimer’s disease, dietary anthocyanin supplementation (12 mg/kg body weight/day) for 30 days improved performance in the Morris water maze and Y-maze task, as well as memory-related pre- and post-synaptic protein markers." (PMID 37764696, 2023). "The associations of non‐pathogenic variants of APP, PSEN1, and PSEN2 with Alzheimer's disease (AD) remain unclear." (PMID 36217304, 2023). "Our findings indicate that aging disrupts the processing of social olfactory cues decreasing social odor exploration, discrimination, and habituation in both wild-type senescent (2-year-old) mice and in 1-year-old double mutant model of Alzheimer’s disease (APP/PS1)." (PMID 37129797, 2023). "This work highlights the importance of keeping APP processing under tight control, to ensure the normal functioning of glutamatergic synapses, being particularly relevant to understand age‐related synaptic impairments and Alzheimer's disease." (PMID 36704841, 2023). "APBA2, the amyloid ß precursor protein binding A2 (aka X11ß, MINT2), is principally recognized for its role in synaptic vesicle exocytosis and its ability to stabilize amyloid precursor protein (APP), and is considered part of the genetic signature of Alzheimer's disease in Down syndrome." (PMID 37303712, 2023). "Thus, it is still to be determined how APP is targeted to the ER and what partners are involved in its transport; this can shed light on early APP biogenesis and its possible effect on Alzheimer’s disease onset." (PMID 37834241, 2023). "Interestingly, the Lep-HFD group exhibited reduced expression of Psen1, coding for a crucial protein linked to the metabolism of the amyloid precursor protein (APP) and associated with Alzheimer’s disease (AD)." (PMID 38203399, 2023). "There was also exited Alzheimer’s disease-like neuropathology: an increased level of soluble amyloid precursor protein β (APPβ) and APP and a decreased level of soluble APPα, suggestive of a shift towards amyloidogenesis in APP processing, which is similar to Alzheimer’s disease." (PMID 37175515, 2023). "Amyloid-beta precursor protein (APP) targeted by the monoclonal antibody aducanumab in the treatment of Alzheimer’s disease (AD) was ranked 506 (top 2.7%) prior to and 152 (top 0.8%) after diffusion on the STRING network (r = 0.6) based on the eQTL-GWAS method." (PMID 37492104, 2023). "The major component of plaques found in the brains of patients with Alzheimer ́s disease (AD) are 40–42 amino acids long amyloid beta (Aβ) peptides derived from the amyloid precursor protein (APP) by enzymatic cleavage, first with β-secretase (BACE1) and then by γ-secretase." (PMID 37542303, 2023). "Over the past few years, the role of SP has been intensely investigated in different systems such as inflammatory bowel disease (IBD), in motor and non-motor Parkinson’s disease (PD), and amyloid precursor protein (APP) metabolism in an Alzheimer’s disease (AD) model." (PMID 37408182, 2023).
Alzheimer disease (continued). "Amyloid Precursor Protein (APP) is a type I transmembrane protein mainly known as the precursor of amyloid-β (Aβ) peptide, the main component of the plaques found in patients affected by Alzheimer’s disease (AD)." (PMID 36768625, 2023). "The cleavage of APP has been characterized to be one of the hallmarks of Alzheimer’s disease (AD)." (PMID 35163117, 2022). "Here, we provide the first proof of concept in the APP/PS1 mouse model of Alzheimer’s disease (AD)." (PMID 36012525, 2022). "The amyloid-β (Aβ) peptide is a major component of plaques in the brain of Alzheimer’s disease patients and is produced through the processing of the amyloid precursor protein (APP) by β- and γ-secretases; Aβ1–40 is the most abundant peptide, and Aβ1–42 is a major component of amyloid plaques." (PMID 35892582, 2022). "According to the higher relevant Alzheimer disease pathway and genes from network pharmacology results, two targets including amyloid beta precursor protein (APP) and glycogen synthase stimulate 3β (GSK3β) were further validated based on western blot experiments." (PMID 35462916, 2022). "The overall m6A level was elevated in the cortex and the hippocampus of APP/PS1 (Alzheimer’s disease) mice compared to C57BL/6 control mice, and FTO was found to interact with APOE, which was associated with Alzheimer’s disease risk in a prospective cohort study." (PMID 36407103, 2022). "The APP/PSEN1 mouse, a transgenic mouse that overexpresses both the amyloid precursor protein (APP) and presenilin 1 (PSEN1), is a pathological model for amyloid-β plaque formation, a hallmark and a primary pathogenic indicator of Alzheimer’s disease." (PMID 36234722, 2022). "Interactions between Aβ and tau may be central to the development of Alzheimer’s disease while APP/PS1 transgenic mice develop age-related accumulation of plaques and tangles in the brain." (PMID 35782939, 2022). "In Alzheimer’s disease, Aβ is generated from APP through sequential cleavages, first by β-secretase and then by γ-secretase complex, the latter consisting of at least four components: presenilin (PS, PS1 or PS2), Nicastrin, anterior pharynx-defective-1 (APH-1) and presenilin enhancer-2 (PEN-2)." (PMID 36012187, 2022). "Increased expression of miR-155 promotes neuronal autophagy in the diseased brain, which is beneficial to many neurodegenerative diseases, such as Alzheimer’s disease and Parkinson’s disease, by eliminating deposited toxic proteins, such as APP/Aβ and α-synuclein." (PMID 35634460, 2022). "Another study suggested that CEF could improve the cognitive impairments of APP/PS1 mice in the early stage of Alzheimer’s disease by upregulating GLT-1 and Nglutamine transporter 1 (SN1) expression and increasing the activity of the GS enzyme." (PMID 35864981, 2022). "Previous researches showed that rebalancing NIM network was involved in the cognitive improving effects of LW-AFC on Alzheimer’s disease (AD) animal models, including the PrP-hAβPPswe/PS1ΔE9 (APP/PS1) mouse model and senescence-accelerated mouse prone 8 (SAMP8) strain." (PMID 35370743, 2022). "In addition, we crossed the hIL-37tg mouse with an animal model of Alzheimer’s disease (APP/PS1) to investigate the anti-inflammatory properties of IL-37 under chronic neuroinflammatory conditions." (PMID 36040311, 2022). "Alzheimer’s disease (AD) is a progressive neurodegenerative pathology defined as the accumulation of hyperphosphorylated tau (p-tau) protein aggregates within neurons and extracellular amyloid-beta (Aβ), a product of amyloid precursor protein (APP) processing." (PMID 35013145, 2022). "However, if APP is initiated by β- and γ-secretase, then secreted APP-β (sAPPβ) and neurotoxic Aβ peptides are generated, which are often involved in Alzheimer's disease (AD) and neurodegeneration." (PMID 35350428, 2022).